CASR (calcium sensing receptor)
Diseases named in the same sentence as CASR in open-access papers (continued):
Sharing a sentence is not in itself a finding about the gene and the disease.
breast carcinoma (continued). "The link between CaSR and EMT in breast cancer is yet to be explored, but studies have shown that inducing CaSR in colon cancer (where it acts as a tumor-suppressor) inhibits EMT and lower expression in lung adenocarcinomas promotes a mesenchymal phenotype." (PMID 32117726, 2020). "Nevertheless, as Pthlh gene is regulated by a cAMP-response element, it derives that the different CaSR Gα preference following CaSR activation accounts for a decreased and an increased PTHRP production in normal and malignant breast cancer cells respectively." (PMID 29099748, 2017). "These investigators have also reported that activation of the CaSR increased the sensitivity of MCF-7 and MDA-MB-231 breast cancer cells to cell death in response to paclitaxel." (PMID 27746743, 2016). "Previous patch clamp experiments revealed that stimulation of CaSR induces TRPC-like nonselective cation currents in HEK293 cells stably transfected with CaSR and in MCF-7 breast cancer cells." (PMID 24905090, 2014). "This retrospective study enrolled 79 patients who underwent surgical removal of invasive breast carcinoma of no special type (NST) to explore the expression of the CaSR in breast cancer." (PMID 37511437, 2023). "The mechanism by which the CaSR downregulates ER is not fully understood, but the literature indicates that high extracellular Ca2+ levels affect ER transcriptional activity in MCF-7 breast cancer cell lines." (PMID 37511437, 2023). "Unlike the physiological effect of the CaSR in suppressing the secretion of PTHrP, in breast cancer cells, the CaSR acts to stimulate the production of PTHrP." (PMID 37511437, 2023). "High extracellular Ca2+ is known to promote the growth and motility of breast cancer cells via the CaSR, but the mechanisms remain not only complicated, but also poorly understood." (PMID 35355564, 2022). "Despite the role of CaSR is still not clear, it affects diverse breast cancer cells traits such as proliferation, migration and death, and contributes to the pathophysiology of osteolytic bone metastasis making it an interesting subject for further studies." (PMID 35163823, 2022). "The switching of CaSR coupling from Gq/11 and Gi/o to Gs has been suggested to contribute to tumourigenesis as it is only present in malignant breast cancer cells and not in normal mammary epithelial cells." (PMID 34223822, 2021). "It was also seen that unlike in normal breast cells, where activated CaSR couples to Gαi and inhibit adenylyl cyclase with the cAMP decrease, in breast cancer cells CaSR couples to Gαs and stimulate cAMP production." (PMID 29099748, 2017). "In addition, they found that the “AG” or “GG” genotype at SNP rs17251221 was associated with reduced CaSR protein levels in 15 tumors and an increase in the risk of breast cancer in a case-control study of Chinese patients with (n = 217) or without (n = 231) breast cancer." (PMID 27746743, 2016). "Some studies have shown that fully transformed MCF-7 and MDA-MB-231 breast cancer cell lines had higher CaSR levels than the nonmalignant breast cell lines, Hs578Bst and MCF-10A cells." (PMID 27746743, 2016). "Very little is known about the regulation of CaSR expression in breast cancer cells and, therefore, we do not yet understand the mechanisms determining the level of CaSR expression in individual cancers." (PMID 27746743, 2016). "For example, in breast cancer, CaSR activation promotes, rather than reduces, PTHrP production." (PMID 36715180, 2023). "Collectively, higher CaSR expression in breast cancer could suggest a poor prognosis and treatment outcome regardless of the breast cancer subtype." (PMID 37511437, 2023). "Overall, these results suggest that higher CaSR expression in breast cancer could indicate a poor prognosis and treatment outcome, regardless of the subtype of breast cancer." (PMID 37511437, 2023).
breast carcinoma (continued). "In addition to proteins that are directly involved in the regulation of endocrine metabolism and growth factor production, breast cancer cells also overexpress proteins related to vitamin D metabolism and signaling via the vitamin D receptor (VDR) or calcium-sensing receptor (CaSR)." (PMID 35954312, 2022). "Breast cancer cell lines had over-expressed CaSR compared to nonmalignant breast cell lines." (PMID 29099748, 2017). "Interestingly, activation of the CaSR can act synergistically with TGFβ to increase PTHrP secretion in hepatocytes as well as MCF-7 and MDA-MB-231 breast cancer cells, a characteristic that may contribute to the pathogenesis of bone metastasis." (PMID 27746743, 2016). "As noted in the Introduction, the CaSR has been shown to regulate PTHrP production by several cell types, such as astrocytes, ovarian epithelial cells, cytotrophoblasts, hepatocytes, osteoblasts, prostate cancer cells, CaSR transfected HEK293 cells, and breast cancer cells." (PMID 27746743, 2016). "Moreover, the BT474 breast cancer cells, which do not metastasize to the bone, did not respond to CaSR stimulation." (PMID 27303307, 2016). "Furthermore, several studies indicated that TRPC channels are involved in the CaSR stimulation-induced calcium influx in some cell types, such as salivary ductal cells, MCF-7 breast cancer cells, aortic smooth muscle cells, keratinocytes, pulmonary neuroendocrine cells and osteoclasts." (PMID 24905090, 2014). "Activation of the CaSR could have dual effects on disease outcome: On the one hand, activation of the CaSR in human MCF-7 breast cancer cells by extracellular calcium concentrations that are detected in bone at tumor metastasis, enhances expression of the estrogen receptor-alpha." (PMID 23340319, 2013).
secondary hyperparathyroidism (38 papers, 2007 to 2026). Overproduction of parathyroid hormone in response to influence external to the parathyroid glands. "We previously found that homozygosity in the variant allele (A) of CASR polymorphism rs7652589 is associated with more severe secondary hyperparathyroidism." (PMID 31775661, 2019). "HD patients, presenting both dyslipidemia and secondary hyperparathyroidism, seem to be a unique group to study CASR polymorphisms that are associated with calcium disorders and possibly also with dyslipidemia." (PMID 31775661, 2019). "In addition, prior studies showed profound upregulation of the GABAB1R/CaSR heterodimer in hyperplastic PTGs from patients with secondary hyperparathyroidism (SHPT), a clinical cohort where vitamin D deficiency is a significant contributor." (PMID 40492090, 2025). "In addition, primary and secondary hyperparathyroidisms are associated with changes in CaSR expression levels." (PMID 39912052, 2025). "Therefore, secondary hyperparathyroidism and atherogenic dyslipidemia have a common genetic background as CASR polymorphism rs7652589." (PMID 31775661, 2019). "Cinacalcet, a class II calcimimetic that targets the calcium-sensing receptor of the parathyroid gland chief cells, can be used to treat the patient’s secondary hyperparathyroidism." (PMID 40557169, 2025). "Clinically, the PAM molecule evocalcet, used in the treatment of secondary hyperparathyroidism, is bound to the 7TM domain of the CaSR by hydrophobic interactions with residues Phe683, Phe687, Trp817, and Ile840." (PMID 40364353, 2025). "The down-regulation of CaSR in nodular hyperplasia has been confirmed in human patients, diagnosed with secondary hyperparathyroidism." (PMID 35805976, 2022). "The impairment of CaSR expression/functionality is the main culprit of primary and secondary hyperparathyroidism." (PMID 36467702, 2022). "Decreased expression of CaSR in secondary hyperparathyroidism has been demonstrated in an animal model and is associated with hypermethylation of the CaSR and VDR genes." (PMID 35805976, 2022). "Cinacalcet (a calcimimetic drug that increases the sensitivity of CaSR to extracellular Ca+2) is routinely used in the chronic management of secondary hyperparathyroidism in patients on renal replacement therapy." (PMID 33542868, 2021). "Both cinacalcet and etelcalcetide are calcimimetics (positive allosteric CaSR modulators) approved for the treatment of secondary hyperparathyroidism in dialysis patients." (PMID 33542868, 2021). "Cinacalcet, a calcimimetic type II compound, is widely used to treat primary and secondary hyperparathyroidism by targeting the calcium-sensing receptor (CaSR) to reduce the production of parathyroid hormone." (PMID 34880751, 2021). "The calcimimetic cinacalcet-HCL (an allosteric modulator of the calcium-sensing receptor (CaSR) expressed by the parathyroid glands) is one of the most effective treatments for secondary hyperparathyroidism." (PMID 31547340, 2019). "Single nucleotide polymorphisms (SNPs) of calcium-sensing receptor gene (CASR) are predominantly associated with phenotypes of primary and secondary hyperparathyroidism, and with idiopathic calcium nephrolithiasis." (PMID 31775661, 2019). "The second-generation CaSR agonist etelcalcetide (AMG 416) was recently approved for the treatment of secondary hyperparathyroidism." (PMID 30151009, 2018). "Etelcalcetide, a novel peptide agonist of the calcium-sensing receptor, prevents vascular calcification in a rat model of renal insufficiency with secondary hyperparathyroidism." (PMID 29038882, 2017). "Somatic CASR mutations are rare, but parathyroid glands of patients with primary or severe uremic secondary hyperparathyroidism often have reduced CaSR expression." (PMID 27679579, 2016).
secondary hyperparathyroidism (continued). "In the treatment of secondary hyperparathyroidism of chronic kidney disease, calcimimetics - allosteric modulators of the calcium-sensing receptor - inhibit glandular hyperplasia and significantly reduce circulating parathyroid hormone levels." (PMID 23232027, 2012). "Allosteric enhancers of this type have been successfully developed for Class C GPCR’s, e.g. Cinacalcet, an enhancer of the calcium sensing receptor used to treat secondary hyperparathyroidism." (PMID 19305799, 2007). "We showed previously that reduced CaSR expression and increased GABAB1R (encoded by Gabbr1 gene) expression in the parathyroid glands of patients with primary or secondary hyperparathyroidism augmented heterodimerization of the two receptors and increased tonic PTH secretion." (PMID 40492090, 2025). "Finally, calcimimetics are extensively employed in managing secondary hyperparathyroidism in CKD by allosterically enhancing the calcium ion sensitivity of the calcium-sensing receptor (CaSR)." (PMID 39200324, 2024). "Our study implicates that activating CaSR for treatment of secondary hyperparathyroidism, we may suspect that also the severity of atherogenic dyslipidemia will be ameliorated, at least in subjects harboring the rs7652589 risk allele." (PMID 31775661, 2019). "Development of secondary hyperparathyroidism could be due to early disturbances on the local calcium sensing receptor, early decline in parathyroid klotho and possibly lower expression of the vitamin D receptor." (PMID 26566277, 2015). "Moreover, clear evidence has been published that vitamin D3 concentrations, inflammatory cytokines and particularly secondary hyperparathyroidism modify CaSR expression throughout the body." (PMID 25134967, 2014). "Thus, it is possible that FLL and OA+UA might suppress secondary hyperparathyroidism in aged rats via their actions on CaSR in kidney and parathyroid glands." (PMID 30564129, 2018). "Thus, the CaSR is a therapeutic target with the clinically approved calcimimetics or positive allosteric modulators (PAMs), cinacalcet, etelcalcetide, and upacicalcet, which are used to increase the sensitivity of the CaSR to [Ca2+]o in the parathyroid glands to treat secondary hyperparathyroidism." (PMID 39912052, 2025). "In the progression of secondary hyperparathyroidism (SHPT), the expression of CaSR in the parathyroid gland decreases and thus limits the regulation of PTH secretion based on calcium levels." (PMID 35140213, 2022). "The existing CaSR agonists, such as cinacalcet, which is approved by FDA and used to treat secondary hyperparathyroidism, may present a new application to treat LUAD." (PMID 32671062, 2020). "CaSR shows negative correlation with Ki-67 both in secondary hyperparathyroidism and adenoma." (PMID 35805976, 2022). "Secondary hyperparathyroidism begins as an adaptive response to maintain serum calcium and phosphorus homeostasis and is characterized by elevated serum concentrations of parathyroid hormone (PTH) mediated in part via the calcium sensing receptor (CaSR) on the parathyroid gland." (PMID 30875390, 2019). "Secondary hyperparathyroidism (SHPT), commonly develops during stages 3 and 4 of CKD, may lead to cardiovascular calcifications by other mechanisms including an impaired effect of parathyroid hormone (PTH), and a decreased calcium-sensing receptor (CaR) expression on cardiovascular structures." (PMID 39165274, 2024).
colon carcinoma (37 papers, 2005 to 2025). "Use of histone deacetylase inhibitors in colon cancer cell lines most of which poorly express CaSR has implicated the involvement of H3K9 deacetylation in the silencing of CASR in colorectal cancer." (PMID 27679579, 2016). "For example, in parathyroid and colon cancers, CaSR expression is significantly reduced leading to loss of the growth suppression when exposed to elevated extracellular Ca2+." (PMID 27303307, 2016). "In contrast, cinacalcet seems to reduce collagen deposition in models of kidney failure and down-regulation of mesenchymal markers is also associated with CaSR activation in colon cancer cell lines." (PMID 26893368, 2016). "The mechanisms involved in this process advance our understanding of the molecular changes in colon cancer cells accompanying the loss of CaSR." (PMID 25879211, 2015). "For example, in parathyroid adenoma and colon cancers, loss of CaSR expression was reported, leading to uncontrolled growth due to elevated calcium level." (PMID 19602280, 2009). "Reduced or loss of CaSR expression was observed in undifferentiated primary colon cancer cells compared with normal colonic epithelial cells." (PMID 18980667, 2008). "To test the hypothesis that loss of CaSR expression is caused by DNA hypermethylation, we sequenced sodium bisulfite modified DNA from tumor and adjacent mucosa samples from colon cancer patients." (PMID 24691920, 2014). "However, in colon cancer anti-proliferative effects of Ca2+ are lost, and this could be due to loss of CaSR expression during colorectal tumorigenesis." (PMID 24176760, 2014). "The calcium-sensing receptor, expressed in human colon epithelial cells and colon cancer cells, plays a critical role in maintaining calcium homeostasis by regulating the secretion of PTH from the parathyroid glands." (PMID 40420632, 2025). "This confirms our previous findings in colon cancer cells and strongly suggests a direct anti-inflammatory action of CaSR inhibition in the colon." (PMID 39770982, 2024). "In human colon cancer cells, CASR activation downregulates expression of thymidylate synthase (TYMS), a key enzyme involved in DNA synthesis." (PMID 37377737, 2023). "Recently, we have proposed a pro-inflammatory role of the CaSR in the intestine, as stimulation of the CaSR in transfected colon cancer cells with positive CaSR allosteric modulators induced the expression of genes involved in several inflammatory pathways." (PMID 37153788, 2023). "Here, we demonstrate for the first time that activation of the CaSR induces the PGE2 pathway in CaSR-transfected colon cancer cells and in inflamed mouse colons." (PMID 37153788, 2023). "Recently it has been described that activation of CaSR induced the expression and secretion of anti-inflammatory cytokines in colon cancer cells overexpressing CaSR." (PMID 35457141, 2022). "Here, we used HT29 colon cancer cells, which were modified to stably express the CaSR via lentiviral infection (HT29CaSR-GFP) using empty vector infected cells as the control (HT29GFP)." (PMID 34576291, 2021). "We proved that pro-inflammatory effects in colon cancer cells are indeed mediated through CaSR activation." (PMID 34576291, 2021). "HT29 colon cancer cells transfected with the CaSR were treated with both enantiomers of NPS 568 and NPS 2143 alone or in combination, and the expression of CaSR and the pro-inflammatory cytokine interleukin 8 (IL-8) was measured by RT-qPCR and ELISA." (PMID 34576291, 2021). "Pharmacological allosteric agonists (calcimimetics) of the extracellular calcium-sensing receptor (CaSR) have substantial gastro-intestinal side effects and induce the expression of inflammatory markers in colon cancer cells." (PMID 34576291, 2021). "Here, we used 1 μmol/L of each compound, as the initial results using NPS R-568 and NPS R-2143 in these transfected colon cancer cells were obtained using drug concentrations that were previously deemed to be CaSR-selective." (PMID 34576291, 2021).